LAMC2 (laminin subunit gamma 2)
Description:
Binding to cells via a high affinity receptor, laminin is thought to mediate the attachment, migration and organization of cells into tissues during embryonic development by interacting with other extracellular matrix components. Ladsin exerts cell-scattering activity toward a wide variety of cells, including epithelial, endothelial, and fibroblastic cells.
Synonyms: LAMB2T; LAMNB2; nicein-100kDa; kalinin-105kDa; BM600-100kDa; B2T; BM600; CSF; EBR2; EBR2A; JEB3A; JEB3B
Tractability: Antibody: its Gene Ontology location is reachable by antibodies, with high confidence; UniProt places it where antibodies can reach, with medium confidence; UniProt predicts a signal peptide or a membrane-spanning region. PROTAC: ubiquitination databases record sites on it. Other modalities: an approved drug acts on it.
Gene: Protein-coding gene on chromosome 1 (183,186,057 to 183,245,127, forward strand). Ensembl gene ENSG00000058085.
Subcellular location: Secreted, extracellular space, extracellular matrix, basement membrane
Subcellular location (Human Protein Atlas): Endoplasmic reticulum; Golgi apparatus; Predicted to be secreted
Pathways (Reactome):
Extracellular matrix organization: Anchoring fibril formation; Assembly of collagen fibrils and other multimeric structures; Degradation of the extracellular matrix; Formation of the dystrophin-glycoprotein complex (DGC); Laminin interactions; Non-integrin membrane-ECM interactions
Cell-Cell communication: Type I hemidesmosome assembly
Developmental Biology: Developmental Lineage of Pancreatic Ductal Cells
Disease: Attachment of bacteria to epithelial cells
Signal Transduction: MET activates PTK2 signaling
Gene Ontology:
Molecular function: extracellular matrix structural constituent
Biological process: positive regulation of cell migration; positive regulation of cell population proliferation; epidermis development
Cellular component: extracellular matrix; extracellular region; laminin-5 complex; laminin-522 complex; laminin-5B complex; basement membrane
Genetic constraint (gnomAD): Loss-of-function variants: 93 observed, 138.64 expected, observed/expected ratio (o/e) 0.67, 90% interval 0.57 to 0.8. The upper end of that interval is the gene's LOEUF score, 0.8, which puts it in group 3 of 6, group 1 being the genes least tolerant of losing a copy. Missense variants: 1,384 observed, 1,525.9 expected, observed/expected ratio (o/e) 0.91, 90% interval 0.87 to 0.95. Synonymous variants: 502 observed, 561.13 expected, observed/expected ratio (o/e) 0.89, 90% interval 0.83 to 0.96.
Homologues: Orthologues: chimpanzee LAMC2 (99% identical), macaque LAMC2 (96% identical), rat Lamc2 (85% identical), mouse Lamc2 (85% identical), pig LAMC2 (84% identical), guinea pig LAMC2 (84% identical), dog LAMC2 (82% identical), tropical clawed frog lamc2 (46% identical). Paralogues in human: LAMC1 (29% identical), LAMC3 (25% identical), LAMA3 (22% identical), LAMA5 (21% identical), HSPG2 (21% identical), LAMA1 (21% identical), LAMA2 (20% identical), LAMB1 (19% identical), LAMB2 (19% identical), LAMB4 (18% identical), USH2A (16% identical), AGRN (13% identical), and 15 more.
Diseases named in the same sentence as LAMC2 in open-access papers:
LAMC2 is named in the same sentence as 100 diseases in open-access papers, as found by Europe PMC text mining. Sharing a sentence is not in itself a finding about the gene and the disease. The quoted sentences say what the papers report.
pancreatic cancer (33 papers, 2012 to 2026). "Previous research showed that LAMC2 has been linked to various cancers, such as lung cancer, gastric cancer, and pancreatic cancer." (PMID 38989468, 2024). "Of note, elevated serum levels of LAMC2 in patients with pancreatic cancer make it an attractive serum-based diagnostic marker." (PMID 36289544, 2022). "Surprisingly, in previous studies, it has been proved that all of our defined switch genes, including Lamc2, Klk1, Nqo1, Aox1, Tspan1, and Cxcl12, are closely associated with the pancreatic cancer’s progression." (PMID 35180880, 2022). "For the laminin subunits (LAMA3, LAMA4, LAMB3 and LAMC2) that were found to be associated with the prognosis of pancreatic cancer, we further analyzed their TCGA tumor tissue expression profiles." (PMID 31182680, 2019). "In the present study, we initially screened out four differentially expressed subunits (LAMA3, LAMA4, LAMB3 and LAMC2) of the laminin gene family that were found to be associated with the clinical outcome of pancreas cancer patients in TCGA." (PMID 31182680, 2019). "LAMC2 (laminin subunit gamma 2) promotes cell proliferation, invasion and migration in multiple cancers, including pancreatic cancer." (PMID 40362181, 2025). "LAMC2 also correlates with decreased survival, metastasis, and advanced tumor stages in pancreatic cancer." (PMID 39682235, 2024). "The oncogenic capacity of LAMC2 has been well-documented in lung cancer, undifferentiated thyroid carcinoma, cholangiocarcinoma, laryngeal cancer, ovarian cancer and pancreatic cancer." (PMID 37891404, 2024). "This study identifies and validates a novel five-gene transcriptomic signature (LAMC2, TSPAN1, MYO1E, MYOF, and SULF1) as both diagnostic biomarkers and potential drug targets for pancreatic cancer." (PMID 39850570, 2024). "LAMC2, an epithelial basement membrane protein, has been found to be significantly upregulated in various cancer cells, such as pancreatic cancer, lung adenocarcinoma, and esophageal squamous cell carcinoma." (PMID 38365674, 2024). "Recent research has shown that LAMC2 is highly expressed in lung cancer, undifferentiated thyroid carcinoma, cholangiocarcinoma, laryngeal cancer, ovarian cancer, and pancreatic cancer." (PMID 37891404, 2024). "Elevated LAMC2 expression promotes pancreatic cancer invasion and metastasis by enhancing AKT-dependent NHE1 activity." (PMID 39850570, 2024). "High LAMC2 expression in pancreatic cancer defines a highly metastatic stem cell subset with a reduced survival probability." (PMID 36090038, 2022). "The ELISAs revealed that the plasma levels of LAMC2 were significantly higher in pancreatic cancer patients compared to healthy donors, both in the training set and in the validation set (p < 0.0001)." (PMID 35681634, 2022). "Our study identified a tumor-initiating cell population in pancreatic cancer characterized by high levels of LAMC2, which undergoes self-renew and differentiation toward a squamous-like phenotype." (PMID 36289544, 2022). "Gene silencing of the LAMC2 gene in pancreatic cancer cell lines inhibited proliferation, migration and invasion ability in vitro and enhanced sensitivity to gemcitabine." (PMID 35681634, 2022). "Histopathological evidence shows that ITGA2, LAMB3, and LAMC2 are expressed exclusively from pancreatic cancer cells." (PMID 34007003, 2021). "THBS2 and VCAN were expressed in both stromal and pancreatic cancer cells, whereas ITGA2, LAMB3, and LAMC2 were solely expressed by pancreatic cancer cells." (PMID 34007003, 2021). "For example, there is ongoing research concerning the LAMC2 overexpression in various human malignancies, including lung cancer, gastric cancer, pancreatic cancer, and cutaneous squamous cell carcinoma (SCC)." (PMID 29511340, 2018). "LAMC2 (a major component of laminin-5) has been reported to be highly expressed in several types of invasive tumors including carcinomas of the pancreas, tongue, colorectal, lung, cervix, lung, extra hepatic cholangiocarcinoma." (PMID 27280700, 2016).
pancreatic cancer (continued). "Overall, LAMC2 is ranked second in the combined results and is, according the to literature, a purported pancreatic cancer gene." (PMID 23365541, 2012). "LAMC2-expressed cells exhibit a higher migration and invasion ability in pancreatic cancer." (PMID 38818308, 2024). "Moreover, studies have indicated that LAMC2 is involved in acquired drug resistance, including platinum and gemicitabine resistance for ovarian and pancreatic cancer patients, respectively." (PMID 37891404, 2024). "In conclusion, pancreatic tumors release LAMC2 and PTX3, which can be quantified in the systemic circulation, and may be useful in selecting patients for further diagnostic imaging." (PMID 35681634, 2022). "Interestingly, a previous report confirmed that LAMB3 and LAMC2 were exclusively derived from pancreatic cancer cells." (PMID 34007003, 2021). "The overexpression of LAMC2 had been shown to be a predictive marker of pancreatic cancer." (PMID 28611293, 2017). "Besides, we have introduced two biologically relevant triplets, namely Klk1 and {Gh1, Cst3} and Lamc2 and {Dhps, Ccr7}, which may be specifically involved in the onset of pancreatic cancer." (PMID 35180880, 2022). "In pancreatic cancer cells, for example, LAMC2 (laminin subunit gamma-2) stimulates Akt-Ser473 phosphorylation, up-regulating NHE1 expression." (PMID 40948941, 2025). "LAMC2 protein levels have been found elevated in the serum of patients with liver cancer, non-small cell lung cancer (NSCLC), pancreatic cancer, etc." (PMID 37891404, 2024). "The protein expression of hub genes was higher in pancreatic cancer tissue than in normal pancreatic tissue samples, wherein ITGA2, LAMB3, and LAMC2 were exclusively expressed in pancreatic cancer cells." (PMID 34007003, 2021). "The function of the ABP destrin has been reported to be affected by LAMC2/NHE1 signaling, and its receptors are highly expressed in pancreatic cancer tissues and cells." (PMID 34194957, 2021). "LAMC2 phosphorylates Akt-Ser473 to promote NHE1 expression, activity, and cell membrane accumulation in pancreatic cancer cells." (PMID 34194957, 2021). "Oncomine analysis of cancer vs. normal tissue confirmed that COL12A1, FN1, ITGA2, LAMB3, LAMC2, THBS2, and VCAN were significantly overexpressed in pancreatic cancer from different datasets." (PMID 34007003, 2021). "It was also observed that ITGA2, LAMB3, and LAMC2 were the only proteins expressed in pancreatic cancer cells but not in stromal cells." (PMID 34007003, 2021). "Moreover, in the Pei pancreas dataset, COL12A1, FN1, ITGA2, LAMB3, LAMC2, THBS2, and VCAN mRNA expression levels were higher in pancreatic cancer tissue than in normal pancreatic tissue samples." (PMID 34007003, 2021). "The microRNA and its target were important regulatory mechanism for LINC00511, such as miR-185-3p/E2F1 in breast cancer, miR29b-3p/VEGFA in pancreatic cancer, miR-15a-3p/Wnt signaling pathway in bladder cancer, miR-765/APE1 in osteosarcoma and miR-765/LAMC2 in tongue cancer." (PMID 31434692, 2019). "An overview of the TMA scores shows that TFF1, LAMC2 and AHNAK2 can be detected in pancreatic cancer samples with a score > 0 in 92, 93, and 53% of all samples, respectively, whereas at least one of the markers was detectable with a score > 0 in 99% of the samples." (PMID 29675033, 2018). "Moreover, such an interaction was revealed in four out of five tested non‐iCCA cancer cell lines, and silencing LAMC2 also reduced the EGFR protein translation, especially in pancreatic cancer cell line Panc‐1, lung cancer cell line H1975 and colorectal cancer cell line HCT‐116." (PMID 38526177, 2024). "Furthermore, LAMC2 and TGM2 have been found to promote the migration of pancreatic cancer cells." (PMID 34485257, 2021).
pancreatic cancer (continued). "In vitro, we confirmed the absence of LAMC2 expression (gene and protein) in Normal Pancreatic cancer cells (i.e., HPNE compared to two established pancreatic cancer cell lines (L3.6pl and PANC-1) and two human PDAC-derived primary cultures (#215 and #253)." (PMID 36289544, 2022). "The other proteins in these pathways were members of the families of interleukin (ITGA2, ITGB6), laminin (LAMC2), and collagen (COL1A1/2, COL6A3), together with cartilage oligomeric matrix protein (COMP), whose role in pancreatic cancer has not yet been clarified." (PMID 33194391, 2020).
gastric cancer (19 papers, 2012 to 2024). A primary or metastatic malignant neoplasm involving the stomach. "In gastric cancer cell lines and tissues, LAMC2 gene expression and DNA methylation analysis revealed that DNA hypomethylation was linked to LAMC2 up-regulation." (PMID 37636564, 2023). "LAMC2 expression is significantly upregulated in gastric carcinoma, pancreatic ductal adenocarcinoma, and in various HNSCC types." (PMID 39201614, 2024). "This agrees with previous studies reporting an increased expression of LAMC2 in several cancer, such as hepatocellular and stomach carcinoma, as well as in lung cancer." (PMID 35878242, 2022). "LAMC2 (Laminin γ2) mediated the Wnt5a-induced invasion of gastric cancer cells." (PMID 27534621, 2016). "In gastric cancer, PCDH8 promotes invasion and metastasis through enhanced interaction with extracellular matrix receptors, possibly through upregulation of laminin subunit gamma-2." (PMID 38368303, 2024). "Recent results suggest that LAMC2 could function as an oncogene to enhance the progression of many types of cancer, including penile squamous cell carcinoma, esophageal squamous cell carcinoma, gastric cancer, tongue squamous cell carcinoma, and colorectal cancer." (PMID 32554866, 2020). "Moreover, knockdown of LAMC2 was able to inhibit EGFR phosphorylation as well as its downstream targets ERK and AKT in pancreatic, anaplastic thyroid carcinoma, and gastric cancer cells." (PMID 37542131, 2023). "Furthermore, we found an overexpression of ITGA2, which regulates Metastases and EMT, LAMC2 and WNT5A genes, that mediate invasion of gastric cancer cells." (PMID 34012923, 2021). "In addition, a study on gastric cancer has suggested LAMB3 and LAMC2 chains accumulate intracellularly and are related with cancer progression, while epigenetic silencing of the LAMA3 chain may lead to an inability of synthesizing the basement membrane, which may affect cancer cell invasion." (PMID 31182680, 2019).
esophageal squamous cell carcinoma (17 papers, 2018 to 2025). Esophageal squamous cell carcinoma (ESCC) is a type of esophageal carcinoma (EC) that can affect any part of the esophagus, but is usually located in the upper or middle third. "Upregulated expression of LAMC2, an indicator of progression in esophageal squamous cell carcinoma (ESCC), is caused by lncRNA Cancer Susceptibility 9 (CASC9) interacting with CREb-binding proteins and is common in patients." (PMID 37889117, 2023). "Concurrently, hypoxic conditions have been demonstrated to foster an increase in histone H3K9la and potentiate the transcription of LAMC2, promoting the proliferation of esophageal squamous cell carcinoma (ESCC)." (PMID 39867891, 2024). "As a unique subunit of LM-332, LAMC2 has been reported to be up-regulated in esophageal squamous cell carcinoma and ovarian carcinoma." (PMID 36612197, 2022). "Additionally, lactylation modification of histone H3K9 (H3K9la) acts as an activating epigenetic mark, facilitating the recruitment of transcriptional coactivators to the LAMC2 promoter and thereby enhancing the proliferation and migration capabilities of esophageal squamous cell carcinoma." (PMID 41458606, 2025). "For example, lncRNACASC9 encourages the metastases of ESCC (esophageal squamous cell carcinoma) by interacting with CREB-binding protein to upregulate LAMC2 expression." (PMID 36262998, 2022). "In addition, a positive correlation between LAMC2 and lncRNA CASC9 was demonstrated, which was consistent with the study published in 2018, showing that lncRNA CASC9 and LAMC2 have positive correlation in esophageal squamous cell carcinoma by interacting with CREB-binding protein." (PMID 34612783, 2021). "LAMC2 binds to integrins α6β4 and phosphorylates FAK, and activates downstream signaling pathways, such as those already reported in esophageal squamous cell carcinoma and breast cancer." (PMID 38475740, 2024). "CASC9 activates LAMC2 expression through altering LAMC2 promoter H3K27me3 level by recruits CBP and subsequently promotes esophageal squamous cell carcinoma metastasis." (PMID 32677984, 2020). "Furthermore, LAMC2 induces activation of the PI3K/Akt signal pathway through the stimulation of the focal adhesion kinase, thereby promoting esophageal squamous cell carcinoma metastasis." (PMID 38243116, 2024).
colorectal cancer (16 papers, 2006 to 2025). A primary or metastatic malignant neoplasm that affects the colon or rectum. "Expression of the LAMC2 chain is associated with worse survival in oesophageal squamous cell carcinomas, oral squamous cell carcinomas, and colorectal carcinoma." (PMID 37779898, 2023). "The rs2147578 C > G polymorphism in the lncRNA gene Lnc-LAMC2–1:1 is associated with susceptibility to several types of cancer, and functional polymorphism in lnc-LAMC2–1:1 may confer a high risk of colorectal cancer through affecting miRNA binding." (PMID 30285664, 2018). "A recent study also found that a functional variant in lnc‐LAMC2‐1:1, a long noncoding RNA (lncRNA), may confer risk of colorectal cancer by affecting miRNA‐binding." (PMID 27334422, 2016). "The alteration on these modifications impacts on the stability and translation of downstream targets of ZFAS1 (such as EIF4A3 and LAMC2), which directly impacts the development of colorectal carcinoma (CRC)." (PMID 38406265, 2024). "In previous studies, LAMB3 has been reported to interact with LAMC2 to form the β3γ2 heterodimer in the cytoplasm of colorectal cancer cells and thus contribute to cancer cell budding." (PMID 36612197, 2022). "The accumulating evidence in this regard revealed that the signalling network mediated by Lamc2 plays key roles in the progression, invasion, and migration of multiple kinds of cancers such as pancreas, stomach, tongue, bladder, and colorectal cancers." (PMID 35180880, 2022). "LAMC2 expression upregulation was usually associated with worse prognosis for patients with head and neck squamous cell carcinoma (HNSC), colorectal cancer, lung adenocarcinoma and bladder cancer." (PMID 34512203, 2021). "High expression levels of LAMC2 have been reported in various cancer types such as lung carcinoma, colorectal carcinoma, and pancreatic cancer." (PMID 33931671, 2021). "In colorectal cancer, stable overexpressed LAMC2 promotes proliferation, migration, and invasion of cancer cells." (PMID 31191455, 2019). "Surprisingly, there were several other pairs containing other than LAMA4, LAMC1, and LAMC2 genes with similar prognostic power in colorectal cancer." (PMID 29504916, 2018). "Several independent groups have demonstrated prognostic value of LAMC2 in colorectal cancer before." (PMID 29504916, 2018). "At the invasive front of colorectal carcinoma the cytoplasmic accumulation of LAM5γ2 in neoplastic cells is the result of synergistic activation of the LAMC2 gene by β-catenin, TGFβ1, and hepatocyte-growth factor (HGF), molecules that all have been variably involved in the pathogenesis of IPF/UIP." (PMID 16813649, 2006).